CD4 (CD4 molecule)
Diseases named in the same sentence as CD4 in open-access papers (continued):
Sharing a sentence is not in itself a finding about the gene and the disease.
tumor (continued). "Moreover, dietary restriction can restore some of the age-related decline in anti-tumor function of CD4+ T cells and responsiveness to OX40 immunotherapy." (PMID 33170123, 2020). "Tumor hypoxic regions can recruit immunosuppressive cells such as myeloid derived suppressor cells (MDSC), tumor-associated macrophage (TAM) and Tregs, and can inhibit the activation of CD8+T cells and CD4+T cells." (PMID 33344235, 2020). "Similar effects were observed in tumor CD4+ effector T cells." (PMID 33747894, 2020). "Interestingly, when comparing the proportion of tumor-reactive CD8+ TILs to CD4+ TILs, a significant difference in favor of CD8+ TIL responses was observed when pooling all cohorts together (p < 0.0001, n = 177)." (PMID 33198174, 2020). "Interestingly, combination treatment of CEA-TCB and anti-PD-L1 blocking antibody increased the intra-tumor frequency of both CD4 and CD8 T-cells compared with monotherapies and vehicle control." (PMID 33330050, 2020). "Our working hypothesis is that CD4 memory help functions directly influence PD‐L1/PD‐1 efficacy over anti‐tumor CD8 responses." (PMID 32648370, 2020). "Inhibition of the PI3K signaling pathway by BKM120 inhibited tumor growth and lung metastasis by enhancing anti-tumor immunity by decreasing the number of CD4+ TILs, increasing the number of activated CD4+CD69+ T cells, and decreasing the number of CD20+ B cells." (PMID 32570871, 2020). "Furthermore, immunosuppressive cell populations (PD1+ CD8 T cells, PD1+ CD4 T cells, Tregs, MDSCs, and M2 macrophages) in tumor-bearing mice immunized with RAH + BHSSC or IDG + BHSSC were not significantly altered." (PMID 32153559, 2020). "PSMB8 and PSMB9 overexpression was found to highly associate with CD4+ and CD8+ T-cell infiltration, regulatory T-cells, NK cells and M1-macrophages, in agreement with a role for IP subunit overexpression in enhancing the immune response in the tumor." (PMID 32060274, 2020). "In addition, IHC staining indicated an increase in tumor-infiltrated CD4+ and CD8+ lymphocytes in both 8 Gy-sEV-immunized ICR and BALB/c mice compared to that in control mice in both models." (PMID 32308755, 2020). "CD4+ T cell subsets also play critical roles in tumor immunology and immunotherapy." (PMID 32457745, 2020). "CD8+Tc1 and CD4+Th1 cells are the main mediators of adaptive anti-tumor immune responses." (PMID 32824521, 2020). "Similarly, CD4+ T cells can directly act by eliminating tumor cells through cytolytic mechanisms, or indirectly by modulating the tumor microenvironment." (PMID 32850346, 2020). "In addition, tumor‐specific CD4+ and CD8+ T cells increase phosphoenolpyruvate (PEP) production by overexpressing phosphoenolpyruvate carboxykinase 1 (PCK1), thereby inhibiting sarco/ER Ca2+‐ATPase (SERCA) activity." (PMID 34766109, 2020). "To further elucidate the role of tumor milieu associated with the 7-IRG signature, we analyzed the estimations of six types of immune cells and observed increased abundance of CD4+ T cells, CD8+ T cells, macrophage, neutrophil and dendritic cells in the high-risk group." (PMID 32117435, 2020). "In summary, BGRDs in CD4+ T cell are associated with oncogenes but not with tumor suppressors or CD4+ T cell specific pathways." (PMID 33144558, 2020). "However, the role of CD4+ T cells in PD-L1/PD-1 blockade-induced anti-tumor responses has been less documented." (PMID 33329566, 2020). "The administration of agonistic CD40 alone or in combination with RT leads to a significant increase in CD8+ and CD4 + T-cells infiltrating the tumour, and the combined approach may successfully induce T-cell dependent immunity." (PMID 33148287, 2020). "Interestingly, we found that immune anti-tumor CD4+ T cells were equally, and, in many cases, even more potent than immune anti-tumor CD8+ T cells in protecting naïve animals from parental tumor take and growth." (PMID 33138029, 2020).
tumor (continued). "Furthermore, CD4 Th1 cells also activate innate anti-tumor responses by NK and type-1 anti-inflammatory macrophages, promoting tumor cell killing and providing a source of TAAs for T cell priming." (PMID 33329566, 2020). "Furthermore, OvC-PDE derived from tumours with immune infiltrate preserved the tumour infiltrating lymphocytes (TILs), namely CD4+ and CD8+ T cells." (PMID 33173111, 2020). "Tumor‐infiltrating CD4+ T helper cells and CD8+ cytotoxic T cells are functionally compromised." (PMID 32994998, 2020). "For example, could a specific correlate of protection be shown in vivo in the tumor tissue and, importantly, could CIITA-tumor cells function as APC to directly prime tumor–specific virgin CD4+ Th cells in vivo?" (PMID 33138029, 2020). "In order to verify the significance of the data, further tumor models will be needed, and future findings may have clinical importance with regard to the fact that many tumor patients are treated with CD4 T-cell-sensitive immunosuppressive agents." (PMID 31936595, 2020). "In 2015, a study reported that migration of tumor-derived exosomes and dendritic cell (DC)-derived exosomes to the lymph nodes could activate CD4+ and CD8+ T cells, leading to the stimulation of anti-tumor responses." (PMID 33235701, 2020). "Mechanistically, CD4 T cells may directly kill the tumor cells by recognition of MHC II presented antigens which causes the release of lytic enzymes as perforin and granzyme or FAS/FAS ligand induced cell death." (PMID 32799890, 2020). "The frequency of total CD4+FOXP3+ lymphocytes as well as regulatory T cells was significantly greater in patients with at least one tumor-involved lymph node compared to those with tumor-free nodes (P = 0.026 and P = 0.036, respectively)." (PMID 33305045, 2020). "Moreover, CD4+ T cells trigger the activation and activity of tumor-infiltrating macrophages and are necessary to the adequate establishment of long-term memory CD8+ T cells." (PMID 32075343, 2020). "However, overall the in vivo data are in agreement with the in vitro data showing a change in CD4+ T cell cytokine expression in mouse tumors along with a protective role with decreased tumor volume in the presence of G-CSFR−/− T cells." (PMID 33042110, 2020). "In addition, CEA-TCB treatment increased the frequency of intra-tumor CD4 and CD8 T-cells expressing CXCR3, a key receptor regulating T-cell chemotaxis." (PMID 33330050, 2020). "It is a long‐standing fact that proficient CD8 anti‐tumor responses largely depend on CD4 help." (PMID 32648370, 2020). "In addition to studies focusing on cDC1s, a scRNA-seq study on mouse and human tdLN samples identified two subpopulations of migratory cDC2s that were directly responsible for the priming of tumor antigen-specific CD4+ TH cells." (PMID 33329692, 2020). "Surprisingly, when it comes to personalized neoantigen vaccines, it has been suggested that the majority of the immunogenic mutanome is recognized by CD4+ T cells in tumor-bearing C57BL/6 mice 62, further emphasizing the necessity of involving CD4+ T cell responses in anti-tumor immunity." (PMID 32483434, 2020). "We speculated that, like Tfh‐like cells, AITL tumor cells suppressed the conventional CD4+ T cells, via IL10 and transformin growth factor β (TGF‐β)." (PMID 31793218, 2020). "Even worse, the majority of CD4+ tumor-infiltrating T cells suppress immune response in GBM, which may explain the phenomenon that resting and activated CD4+ T cells are both higher in high-risk immune group." (PMID 32133292, 2020). "Another explanation for these cytokines may be that those pro-inflammatory cytokines are secreted by macrophages and may initiate adaptive immune responses through the polarization of CD4+ T cells towards Th1 phenotypes, thus exhibiting anti-tumor activity." (PMID 33036138, 2020). "Interleukin-17 (IL-17) from a distinct subset of CD4+ T cells may significantly induce cancer-elicited inflammation to prevent tumor immune surveillance." (PMID 33415169, 2020).
tumor (continued). "Finally, flow cytometry was used to analyze immune cell populations in the tumor masses including CD4+, CD8+, and regulatory T cells in addition to natural killer cells." (PMID 32596146, 2020). "This is strongly supported by a recent study showing that tumor-derived TGF-β could suppress the anti-tumor function of CD4+ T cells through SMAD protein phosphorylation in the tumor effusion fluids of metastatic patients." (PMID 33117674, 2020). "Among the CD4+ T cells, Treg cells play a significant role in cancer immune evasion by blocking the induction of immune response against tumor antigens in the periphery as well as by neutralizing tumor-infiltrating effector T cells." (PMID 32552719, 2020). "Through the T cell-based anti-tumor mechanisms investigation, compared to siPD-L1 or 1MT control group, Co-CHL treatment contributed to more numbers of intratumoral CD8+ T cells, and higher CD8+/CD4+ T-cell ratio, resulting in stronger tumor regression and higher therapeutic efficacy." (PMID 32408880, 2020). "The mechanisms of tumor protection by CD4 T cells stem from studies in mice." (PMID 32630460, 2020). "However, the percentages of CD3+CD4+ T cells in the spleen (56.27% vs 58.1%, respectively, NS) and the percentages of total T cells in the tumor-infiltrating cell populations (36.73% vs 33.67%, respectively, NS) did not significant changes." (PMID 32425796, 2020). "Indeed, we observed the preferential infiltration by Mo-MDSC, macrophages and eosinophils among myeloid cell subsets and by CD8+ and CD4+ T cells over Tregs into the tumor tissue of mice treated with CTX + PDL1/2 therapy as compared to the other treatments." (PMID 32290265, 2020). "Tumours in Fgf2LMW−/− mice contained increased proportions of CD4+ and CD8+ T cells." (PMID 32792542, 2020). "However, in most cancers, the tumor microenvironment is infiltrated by TAMs that, in cooperation with regulatory CD4+ T cells, creates an immunosuppressive microenvironment and inhibits the activated T effector cells." (PMID 32326073, 2020). "We sought to determine whether IL-2 controls GzmB expression in adoptively transferred tumor-reactive CD4+ T cells in vivo." (PMID 31924474, 2020). "Murine models also demonstrated Th17 CD4+cells are capable of tumor eradication." (PMID 33362774, 2020). "Among varying subsets of TILs, the CD4+ T cells accounted for a great proportion and may play an important role in the tumor microenvironment." (PMID 33469515, 2020). "Tumor-Evoked Regulatory B Cells (tBreg) exert antitumor activity by promoting conversion of the resting CD4+ T cell into FoxP3+ Treg by secretion of TGF-β then the Treg inhibit T cell proliferation and promote tumor metastasis by suppression of the anti-tumor effects of CD8+ T cells and NK cells." (PMID 32664587, 2020). "However, a role in tumor control is also played by the CD4+ T cell compartment, as reflected by the observation that CD4+ T cells infiltrate the tumor, and by the prognostic value of several CD4 subsets in different malignancies." (PMID 32265933, 2020). "B cells exhibit antitumor functionality by directly killing tumor cells, producing specific antibodies for tumor antigens, acting as antigen-presenting cells (APCs) for T cell activation and memory T cell development, and facilitating CD4+ and CD8+ T cell immune responses." (PMID 31991604, 2020). "Tumor cells, dendritic cells, CD4+ and CD8+ T lymphocytes have been selected as the main players." (PMID 33281620, 2020). "Moreover, findings in GBM murine models showed that pharmacological targeting of MDSCs by Sunitinib resulted in significantly increased CD3+CD4+ T cell count in the tumor microenvironment." (PMID 32765498, 2020). "Moreover, in C51 tumor-rejecting mice a statistically significant expansion of spleen IFNγ-secreting CD4+ T helper (TH) type 1 cells and F4/80+ macrophages were observed when compared to both P and E C51-injected control mice." (PMID 32197460, 2020).
tumor (continued). "Interestingly, in-vivo anti-tumor function of pmel-I and OT-1/2 T cells was improved by CTLA-4:CD28 expression, but was highly dependent on the presence of CD4+ T cells, and was linked to their elevated production of IL-2." (PMID 32570906, 2020). "This was likely due to an enhanced immunological response against the tumor, consisting in the accumulation of CD4+ T cells in mesenteric and tumor draining lymph nodes and in tumor bed, and in the increased secretion of IL-12, which normally synergizes anti-PD1 therapy." (PMID 32523887, 2020). "Moreover, the combination therapy also increased the number of tumor-infiltrating CD4+ T cells by 5.76-fold, whereas anti-PD-1 and JX monotherapy increased infiltrating CD4+ T cells by 1.71-fold and 3.37-fold, respectively when compared with the controls." (PMID 33199510, 2020). "Indeed, macrophages were shown to function as APCs and thereby activate the CD8+ T cell population while decreasing priming of CD4+ T cells after anti-CD47-induced phagocytosis of tumor cells." (PMID 32983165, 2020). "On the other hand, given the positive association between the presence of lymphoid markers (CD3, CD4, and CD8) and HLA tumor expression, only the low inflammatory subset seems to have the ability to develop an effective T cell infiltrate whenever HLA antigen expression on tumor cells is retained." (PMID 32646072, 2020). "The histological analysis of MOC1 tumor one week after treatment showed that infiltration of CD8+ and CD4+ T-cells into the tumor bed dramatically increased after CTLA4 immune-checkpoint blockade alone and combined regimen of CD44-targeted NIR-PIT with CTLA4 immune-checkpoint blockade." (PMID 32937841, 2020). "Whereas correlation analysis did not suggest an association of tumor weight and T cell frequencies in spleen, higher CD4+ and CD8+ T cell frequencies in the blood of animals showed a significant and negative correlation with tumor weight (not shown)." (PMID 32610710, 2020). "It is tempting to speculate that increasing the frequency of tumor-specific CD4 T helper cells might provide a selective advantage to both naturally occurring and ACT-derived TM." (PMID 32973794, 2020). "CD4+ T cells have been proven to participate in anti-tumor immunity and improving prognosis." (PMID 33043022, 2020). "Furthermore, CD4+ T cell suppression and Treg expansion were reduced upon PD-L1 inhibition during co-culture with ICB NR tumor-associated myeloid cells." (PMID 32071302, 2020). "The same phenomenon was also observed in the K7-derived syngeneic mouse model, as microRNA-200a promoted tumor growth by increasing the percentage of Foxp3+ regulatory T lymphocytes while reducing the proportions of CD4+, CD8+, and IFN-γ+ cytotoxic T lymphocytes." (PMID 31981455, 2020). "Thus, CD4 T cells can kill tumor target cells (i) that constitutively express MHC-II molecules via direct MHC-II/peptide recognition or (ii) indirectly by inducing MHC-II expression via IFN-γ." (PMID 32630460, 2020). "Similarly, IL-7 can prolong the survival of CD4+ effector/memory T cells and strengthen anti-tumor activity of CD4+ T cells." (PMID 33329531, 2020). "The results suggested that there may exist some CD4+CD25+ T cells that promote tumor genesis and metastasis in the tumor primary and metastatic tissues." (PMID 33029539, 2020). "Importantly, exposure of CD4+ CD171-specific CAR T cells to tumor-derived extracellular vesicles significantly impaired tumor cytotoxicity of CAR T cells." (PMID 32296437, 2020). "One of the mechanisms which could explain Th17 cell prevalence among TILs is a direct polarization of CD4 T cells into Th17 under the influence of cytokines produced by the tumor microenvironment." (PMID 32121394, 2020). "Furthermore, the expression levels of PLOD1–3 were positively correlated with the activities of tumor-infiltrating immune cells, including macrophages, neutrophils, CD4+ T cells, and dendritic cells." (PMID 33014843, 2020).
tumor (continued). "However, the longstanding fact that proficient CD8 anti-tumor responses largely depend on CD4 help is often underestimated, or at least overlooked." (PMID 33329566, 2020). "The engineering platforms provide an opportunity to produce cancer-specific CD4+ T cells capable of recognising tumour cells via MHC class-I-restricted TCRs and contribute to protection by directly killing cancer cells and/or by improving the effector function and memory formation of CD8+ T cells." (PMID 32708397, 2020). "Furthermore, we observed an increased population of CD4+ T cells within the orthotopic grown tumor 21 days after induction compared to the subcutaneously grown tumor (p ≤ 0.01)." (PMID 33383676, 2020). "Lineage tracking analysis using TCR repertoire has revealed that the source of these tumor‐infiltrating Treg cells is mostly recruitment from other lymphoid tissues with migration from adjacent tissues and conversion of CD4+ T cells to induced Treg cells providing only a minor component." (PMID 32272497, 2020). "Furthermore, combination therapy significantly reduced the number of CD4+ regulatory T cells (Tregs) in the tumor and decreased their proliferative capacity." (PMID 33256806, 2020). "Indeed, IDO-deficient mice increase CD4+ and CD8+ effector T cell infiltration in the tumor microenvironment and show better anti-CTLA-4 therapy effects than that of the wild-type." (PMID 31968651, 2020). "Notably, GFP+Foxp3+CD4+ T cells were barely detected in tumor, while a substantial population of Tfr was observed in dLNs, suggesting the absence of Tfr population in tumor mass." (PMID 32477338, 2020). "Moreover, FcγR-mediated stimulation of CD4 + T-cells and activation of CD4 + T-cells with HER2-primed dendritic cell vaccines reduced tumor burden through tumor-specific T-cell response." (PMID 33292267, 2020). "In addition, it has been recently demonstrated that PD-1 blockade counteracts the increase of PD-1high CD4+ T follicular helper cells that accumulate at the tumor site and inhibits Teff functions in experimental tumor models." (PMID 32099064, 2020). "In both models CD4+ Th2 cells were shown to mediate the tumor-suppressive effects of TSLP." (PMID 33042121, 2020). "The integration of IL18BP and tumor-infiltrating CD4+ T cells could be a potential target for STAD therapy." (PMID 33469515, 2020). "Both CD8+ cytotoxic T-cells and CD4+ T helper cells play important roles in anti-tumour immunity, with the assumption that CD8+ T-cells are primary effectors because of their enhanced cytotoxic properties, and indeed, as a purified cell product are capable of tumour elimination." (PMID 32824734, 2020). "ICB treatment in both shScr-ST and shIDO-ST groups increased Tregs out of total CD4+ T cells consistent with reports in human tumor treatment; however, shIDO-ST treatment in combination with ICB prevented the level of Treg increase seen in the shScr-ST + ICB treatment group." (PMID 33339195, 2020). "Another CD4+ T cell subset which plays a role in tumor immunity is the Th17 cell subset." (PMID 33276524, 2020). "CD4+ T cell help was required for optimal CTL generation that killed tumor cells." (PMID 33298945, 2020). "In PRAD, LCN2 expression negatively correlated with tumor purity(r = −0.39, P = 1.38e-16) and positively correlated with CD4+ T cells (r = 0.288, P = 2.62e-09), macrophages (r = 0.114, P = 2.00e-02), neutrophils (r = 0.275, P = 1.20e-08), and dendritic cells (r = 0.142, P = 3.82e-03)." (PMID 33425761, 2020). "CD4+ T-helper cells are an integral part of anti-tumour immunity: when activated in the presence of dendritic cell derived type-1 interferon and IL-12, they produce a number of pro-inflammatory (‘TH1’) cytokines, which promote CTL proliferation and thus anti-tumour immunity." (PMID 32157213, 2020). "This may indicate a role for captopril in the activation of CD8+ and DNT but also in suppressing the activation of CD4+ T cells within the tumor." (PMID 32448803, 2020).